IGBP1C (IGBP1 family member C)
Synonyms: IGBP1P2
Gene: Protein-coding gene on chromosome 17 (58,660,424 to 58,692,045, reverse strand). Ensembl gene ENSG00000266826.
Subcellular location (Human Protein Atlas): Microtubules; Primary cilium; Basal body; Cytokinetic bridge
Gene Ontology:
Molecular function: protein phosphatase regulator activity
Biological process: regulation of signal transduction
Cellular component: cytosol
Homologues: Orthologues: macaque IGBP1C (94% identical), dog IGBP1 (83% identical), mouse Igbp1 (77% identical), rat Igbp1 (77% identical), tropical clawed frog igbp1 (55% identical), zebrafish igbp1 (53% identical), Drosophila melanogaster Tap42 (31% identical), Caenorhabditis elegans ppfr-4 (31% identical). Paralogues in human: IGBP1 (85% identical).